CDA (cytidine deaminase)
Diseases named in the same sentence as CDA in open-access papers (continued):
Sharing a sentence is not in itself a finding about the gene and the disease.
lung adenocarcinoma (4 papers, 2015 to 2022). A carcinoma that arises from the lung and is characterized by the presence of malignant glandular epithelial cells. "We took advantage of the publically available TCGA database containing 517 cases of primary lung adenocarcinoma tumors and performed an in-silico mRNA expression analysis of CDA, TYMP and several EMT markers." (PMID 33874986, 2021). "Further analysis based on the overall survival of 502 lung adenocarcinoma patients, revealed that low expression of CDA correlated with a better survival, while TYMP expression levels did not correlate with survival." (PMID 33874986, 2021). "In addition, the overall survival of patients with lung adenocarcinoma with high CDA expression was significantly lower than that of patients with low CDA expression." (PMID 35999456, 2022). "To further understand the association of CDA gene expression with SDHB c.136C>U RNA editing, we evaluated RNA sequencing data in the Cancer Genome Atlas (TCGA) for three randomly chosen cancers, primary head and neck squamous cell carcinoma, lung adenocarcinoma and secondary skin cutaneous melanoma." (PMID 25898173, 2015). "In summary, chemotherapy treatment generally increased CDA and TYMP expression and activity in lung adenocarcinoma cell lines." (PMID 33874986, 2021). "In a summary, CDA and TYMP expression positively correlate with the EMT status in lung adenocarcinoma patient samples." (PMID 33874986, 2021). "Next, we compared the expression of RAC2 and CDA mRNAs between DMSO and U0126 treatments in the three KRAS-mutant lung adenocarcinoma cell lines." (PMID 27846317, 2016).
glioma (3 papers, 2013 to 2022). A benign or malignant brain and spinal cord tumor that arises from glial cells (astrocytes, oligodendrocytes, ependymal cells). "In order to further detect the effect of CDA on the growth and development of glioma cells, K562 cells treated by different plasmids were inoculated into nude mice." (PMID 30002603, 2018). "CDA-carrying NSCs are currently being tested in the first clinical study of feasibility against recurrent high-grade gliomas (NIH trial NCT01172964)." (PMID 24202446, 2013). "Combination of this recombinant CDA with radiotherapy has shown significant tumor cell killing and delayed tumor growth in xenograft models of glioma." (PMID 24202446, 2013). "Additionally, expression of the CDA suicide gene in vivo was reported in the glioma tumor cell inducing DNA damage after addition of 5-FC, resulted in suppression of glioma cell proliferation." (PMID 36164544, 2022).
hepatocellular carcinoma (3 papers, 2020 to 2022). A malignant tumor that arises from hepatocytes. "Although the mutation signals found in liver cancer do not appear to affect genomic DNA, there may be other roles of the nuclear-localized APOBEC3B cytidine deaminase in hepatocellular carcinoma cells, thus requiring additional exploration." (PMID 36203448, 2022). "APOBEC3F, a member of the cytidine deaminase gene family, is thought to play a role in the cell cycle or growth control, and overexpression of APOBEC3F is also related to poor recurrence-free survival of HBV-related hepatocellular carcinoma." (PMID 33634092, 2020).
HIV-1 infection (3 papers, 2016 to 2022). The type species of lentivirus and the etiologic agent of acquired immunodeficiency syndrome (AIDS). "In order to decipher the molecular mechanism regulating this late RT, we explored the role of several key partners of NC, such as Vif, gRNA and the cellular cytidine deaminase APOBEC3G that restricts HIV-1 infection by targeting the RT." (PMID 27273064, 2016). "APOBEC3G is an innate restriction factor that inhibits HIV-1 infection as a cytidine deaminase." (PMID 35563460, 2022). "A3DE cytosine deaminase (CDA) domain is crucial for anti-HIV-1 infection." (PMID 27428332, 2016).
myeloid leukemia (3 papers, 2014 to 2026). A clonal proliferation of myeloid cells and their precursors in the bone marrow, peripheral blood, and spleen. "One former study found that, in many cancers including myeloid leukemia, the CDA expression in male cancer patients was remarkably higher than that in females." (PMID 30002603, 2018). "Resistance to araC in myeloid leukemia cells was repeatedly associated with altered expression of genes involved in nucleotide salvage pathway, including downregulation of DCK, or upregulation of key araC-inactivating enzymes, namely cytidine-deaminase (CDA) or cytoplasmic 5′nucleotidase (NT5C2)." (PMID 24972933, 2014).
acute lymphoblastic leukemia (2 papers, 2023 to 2025). Leukemia with an acute onset, characterized by the presence of lymphoblasts in the bone marrow and the peripheral blood. "Their results showed significant reduction in CDA activity in lymphoblasts from patients with acute lymphoblastic leukemia (ALL), with a correlation between enzymatic activity and the percentage of circulating blasts." (PMID 40869362, 2025).
breast tumors (2 papers, 2018 to 2021). "Apolipoprotein B mRNA editing enzyme catalytic polypeptide-like 3B (APOBEC3B) is a gene editing enzyme with cytidine deaminase activity and high expression of its mRNA in breast tumors have been shown to be associated with progressive cases and poor prognosis." (PMID 30093965, 2018). "In addition, high BLM-expressing breast tumors were positive for signature 13, which has been attributed to APOBEC cytidine deaminase activity." (PMID 34966786, 2021).
chronic myeloid leukemia (2 papers, 2018 to 2023). "CDA gene silencing can inhibit the proliferation of chronic myeloid leukemia cells and induce apoptosis." (PMID 37240761, 2023).
endometriosis (2 papers, 2020). The growth of functional endometrial tissue in anatomic sites outside the uterine body. "Five genes (ANXA4, CDA, CDK10, DST, and HSP90AB1) from the catalogue were reported to be associated with endometriosis at two omics levels, for example ANXA4 gene at transcriptomics and ANXA4 at proteomics level." (PMID 32474803, 2020). "SPP1, LIF, TCN1 and CLDN4 were common to adenomyosis and healthy groups of genes, while ANXA2, EDNR8, MMP26, DEPP1, ABCC3, CDA and SLC1A1 were common to endometriosis and healthy groups." (PMID 32933042, 2020).
esophageal cancer (2 papers, 2021 to 2024). A primary or metastatic malignant neoplasm involving the esophagus. "Furthermore, CDA expression was also significantly upregulated in colon, gastric and esophageal cancers compared to in their normal counterparts." (PMID 38844817, 2024).
glioblastoma (2 papers, 2024 to 2025). The most malignant astrocytic tumor (WHO grade IV). "There are potentially three deaminases that might account for the deamination of 5HmdC in glioblastoma: deoxycytidine deaminase, dCDA, cytidine deaminase, CDA and dCMP deaminase, DCTD." (PMID 40807411, 2025).
Hyperbilirubinemia (2 papers, 2023). An increased amount of bilirubin in the blood. "Studies included in this review reported that CDA rs2072671 and rs1048977 SNPs were significantly associated with overall toxicity, HFS, and severe hyperbilirubinemia." (PMID 36980706, 2023).
measles (2 papers, 2019 to 2021). A highly contagious viral infection caused by the measles virus. "Recently, we found that the cytidine deaminase APOBEC3G (A3G) inhibits measles (MV) replication." (PMID 30621148, 2019). "RNA editing activity of this cytidine deaminase was first demonstrated in human immunodeficiency virus (HIV) and later in measles, mumps and respiratory syncytial virus (RSV)." (PMID 33630927, 2021).
multiple myeloma (2 papers, 2019 to 2023). "Importantly, A3B knockdown profoundly decreased the cytidine deaminase activity of whole-cell lysates from myeloma cells, suggesting that among APOBECs, A3B plays a major role in cytidine deamination-related mutagenesis in myeloma cells." (PMID 31073151, 2019).
neuroblastoma (2 papers, 2022 to 2024). Neuroblastoma (NB) is the most common solid, extracranial childhood tumor. "The genes encoding CDA and several other enzymes related with uracil and cytosine nucleotide metabolism locate to chromosome 1p and 1p deletions are frequent in neuroblastoma." (PMID 36424385, 2022). "According to this comparison, neuroblastoma tumor samples consistently show low levels of CDA expression (Mann-Whitney U test, two-sided, FDR = 0.006) while lung (most studies are on NSCLC) and AML show variable expression levels." (PMID 36424385, 2022). "This led to the finding that the mRNA levels of CDA are consistently low in several cell line types including cell lines derived from childhood cancers such as neuroblastoma." (PMID 36424385, 2022). "In this regard, we detected that the expression of cytidine deaminase (CDA), which converts cytidine into uridine, is low in an important proportion of cancer cell lines and consistently low in neuroblastoma samples and in cell lines from neuroblastoma and small cell lung carcinoma." (PMID 36424385, 2022). "All neuroblastoma cell lines tested were negative for CDA by Western blot analysis." (PMID 36424385, 2022).
Obesity (2 papers, 2021 to 2022). Accumulation of substantial excess body fat. "Cytidine deaminase, the enzyme responsible for deoxycytidine metabolism in the obesity-predictive metabolites, is linked to obesity-associated reduction of immune B-cell responses." (PMID 36458093, 2022). "DIDO1 is only upregulated in the NASH dataset, and lastly, CDA is downregulated in obesity and NASH and upregulated in the other two datasets." (PMID 34833079, 2021). "Additionally, we investigated five genes, PRDM2, CXCL1, PHLDA1, DIDO1, CDA, which were commonly expressed in all datasets including depression, obesity, diabetes, and NASH." (PMID 34833079, 2021). "PTX, CDA, and CXCL were present in the clusters among depression and obesity, and depression and NASH." (PMID 34833079, 2021).
ovarian carcinoma (2 papers, 2022 to 2025). A malignant neoplasm originating from the surface ovarian epithelium. "In fact, APOBEC3B exhibited an upregulation pattern in breast and ovarian cancer cell lines, demonstrating a consistent association between this cytidine deaminase activity and neoplasia." (PMID 36560657, 2022).
pancreatic adenocarcinoma (2 papers, 2016 to 2017). "The reduction of CDA is attributed to nab-paclitaxel, as in vitro experiments in mouse pancreatic adenocarcinoma cells had demonstrated that paclitaxel actually reduced CDA protein levels in cultured cells." (PMID 29144412, 2017). "M2 can mediate gemcitabine resistance of pancreatic adenocarcinoma by upregulating cytidine deaminase." (PMID 26879926, 2016).
rheumatoid arthritis (2 papers, 2018 to 2022). A chronic, systemic autoimmune disorder characterized by inflammation in the synovial membranes and articular surfaces. "Indeed, circulating CDA was shown to be increased in several conditions including septicemia, metastasis and rheumatoid arthritis as well as in systemic lupus erythematosus patients, and whereas uridine levels do not differ, plasma cytidine levels may be lower in adults than in infants." (PMID 36424385, 2022).
systemic lupus erythematosus (2 papers, 2022 to 2024). An autoimmune multi-organ disease typically associated with vasculopathy and autoantibody production. "ABCs, initially discovered in systemic lupus erythematosus (SLE), are CD11c+ B cells with high expression levels of integrin subunit alpha X (ITGAX), T‐bet, and activation induced cytidine deaminase." (PMID 38469546, 2024).
anemia (1 paper, 2025). A reduction in the number of red blood cells, the amount of hemoglobin, and/or the volume of packed red blood cells. "Our patient presented with mild anemia, pallor, dark urine, hepatosplenomegaly with significant splenomegaly, poor growth history, and no significant history of transfusion dependency, which correlates with the presentation described in the literature of CDA III." (PMID 40927401, 2025).
B-cell lymphomas (1 paper, 2018). "Signature 9 (T > G in WT motif with W = A or T), a consequence of activation-induced cytidine deaminase (AID) activity, is also a feature of CLL and B-cell lymphomas." (PMID 29654271, 2018).
beta thalassemia (1 paper, 2015). Beta-thalassemia (BT) is characterized by deficiency (Beta+) or absence (Beta0) of synthesis of the beta globin chains of hemoglobin (Hb). "This cluster includes six patients with congenital anaemias characterised by erythroid cell loss at a stage that is later than BFU-E (i.e. HbS, spherocytosis, CDA II and Beta thalassemia), and five patients with acquired conditions." (PMID 26394034, 2015).
biliary tract cancer (1 paper, 2018). "In addition, CDA was reported to be the prominent enzyme in the metabolism of gemcitabine, a pyrimidine analog widely used in the chemotherapy of tumors such as biliary tract cancer." (PMID 30002603, 2018). "Cytidine deaminase (CDA) is a leading enzyme that participates in the metabolism of gemcitabine, a pyrimidine analog used for chemotherapy in treating tumors such as biliary tract cancer." (PMID 30002603, 2018).
Cirrhosis (1 paper, 2023). A chronic disorder of the liver in which liver tissue becomes scarred and is partially replaced by regenerative nodules and fibrotic tissue resulting in loss of liver function. "Our results showed that several crucial drivers, including regulators that are potentially associated with the progression of cirrhosis, such as SLC40A1, DAB2, FOLR2, GPAT3, and CDA, were upregulated during fibrosis." (PMID 36845083, 2023).
co-infection (1 paper, 2015). "Because there is evidence for cytidine deamination of the PLV genome, we reasoned that elevated levels of cytidine deaminase might reduce FIV replication in some tissues in a co-infection with PLV." (PMID 26123018, 2015).
colorectal tumors (1 paper, 2024). "Conversely, CDA overexpression in CDA-depleted PDACs or anti-PD-1-responsive colorectal tumors or systemic UDP administration (re)establishes resistance." (PMID 38844817, 2024).
COVID-19 (1 paper, 2024). A disease caused by infection with severe acute respiratory syndrome coronavirus 2. "Genes in this pathway, AICDA, CDADC1, CDA and APOBEC3D, were regulated in opposite directions (only AICDA was statistically significantly downregulated in SLE and CDA up in COVID-19), while APOBEC3A and APOBEC3B were significantly upregulated in COVID-19, but not SLE." (PMID 38302132, 2024).
dementia (1 paper, 2025). Loss of intellectual abilities interfering with an individual's social and occupational functions. "The ATP‐binding cassette subfamily A member 7 (ABCA7) gene, linked to dementia in African Americans, and unique genetic variants like those in A‐kinase anchor protein 9 (AKAP9) and cytidine deaminase (CDA) genes, emerge as potential contributors." (PMID 40289851, 2025).
diabetic foot ulcer (1 paper, 2025). "Second, while immunohistochemical staining confirmed the expression of CDA and ODC1 in clinical diabetic foot ulcer samples, the limited sample size necessitates larger cohort studies to validate their diagnostic value and clinical significance." (PMID 41322696, 2025).
gynecological cancers (1 paper, 2025). "In conclusion, our findings indicate that the expression of 6-CRRGs, including APOBEC3B, HELLS, SLC15A3, CDA, RHOB and UPP1, is associated with the prognosis of patients with common gynecological cancers." (PMID 39944833, 2025). "CDA was associated with the pathways of ECM receptor interaction, focal adhesion, complement and coagulation cascades, cytokine receptor interaction, etc., in all these three common gynecologic cancers." (PMID 39944833, 2025).
hemophilia (1 paper, 2016). Hemophilia is a genetic disorder characterized by spontaneous hemorrhage or prolonged bleeding due to factor VIII or IX deficiency. "The recently reported cytidine deaminase-fused Cas9 version that edits specific base without DSBs can be considered as another option to correct specific point mutations, potential causes of hemophilia." (PMID 27357631, 2016).
latent infection (1 paper, 2015). "EBNA2 is important for B cell transformation when EBV establishes its latent infection and is the transactivator of various genes, including LMP1 that activates NF-κB; thus, it is related to antibody production and the expression of activation-induced cytidine deaminase." (PMID 26322262, 2015).
Lymphadenopathy (1 paper, 2013). Enlargement (swelling) of a lymph node. "One other patient had lymphadenopathy and giant germinal centers, indicating a possible activated cytidine deaminase deficiency." (PMID 24373416, 2013).
monocytic leukemia (1 paper, 2024). "In monocytic leukemia cell lines (THP-1 and U937), the results showed an increased ratio of deoxycytidine kinase/cytidine deaminase (dCK/CDA) gene expression, which further enhanced 1-induced DNA damage." (PMID 38535455, 2024).
osteoarthritis (1 paper, 2025). A noninflammatory degenerative joint disease occurring chiefly in older persons, characterized by degeneration of the articular cartilage, hypertrophy of bone at the margins and changes in the synovial membrane. "Serum cytidine deaminase is increased in people with RA compared to those with osteoarthritis and is associated with disease activity." (PMID 40713837, 2025).
papilloma (1 paper, 2021). A benign epithelial neoplasm that projects above the surrounding epithelial surface and consists of villous or arborescent outgrowths of fibrovascular stroma. "In addition, we observed the largest fold increase in C to G and C to T substitutions comparing papilloma to matched normal mucosa, suggestive of APOBEC cytidine deaminase-mediated mutagenesis." (PMID 34931021, 2021).
prostate carcinoma (1 paper, 2022). A carcinoma that arises from epithelial cells of the prostate gland. "In addition, androgen and genotoxic stress recruit cytidine deaminase (AID) and LINE1-encoded ORF2 endonuclease to the specific sites and induce DNA cleavage of TMPRSS2, SLC45A3, ERG, and ETV1 in prostate cancer." (PMID 36579559, 2022).
psoriasis (1 paper, 2018). An autoimmune condition characterized by red, well-delineated plaques with silvery scales that are usually on the extensor surfaces and scalp. "The pro-inflammatory environment of psoriasis results in an antiviral state and the increased expression of antiviral proteins, such as the cytidine deaminase APOBEC3G and phosphohydrolase SAMHD124." (PMID 29531256, 2018).
retinoblastoma (1 paper, 2024). A malignant tumor that originates in the nuclear layer of the retina. "Weri-Rb1 and Y79 are the only retinoblastoma cell lines analyzed in the depmap database, and both express low levels of CDA mRNA." (PMID 38332874, 2024).
sarcoidosis (1 paper, 2024). Sarcoidosis is a multisystemic disorder of unknown cause characterized by the formation of immune granulomas in involved organs. "Finally, sarcoidosis-affected skin was enriched in B cells that expressed CDA and BCL6, 2 genes typically induced during late-stage changes in germinal center differentiation and isotype switching." (PMID 39225100, 2024).
schizophrenia (1 paper, 2021). A major psychotic disorder characterized by abnormalities in the perception or expression of reality. "Tetrahydroxyuridine, a reversible inhibitor of cytidine deaminase, could exacerbate the negative symptoms of schizophrenia." (PMID 34975570, 2021).